TMA16 (translation machinery associated 16 homolog)
Description:
Involved in the biogenesis of the 60S ribosomal subunit in the nucleus.
Synonyms: C4orf43; FLJ11184
Tractability: Small molecule: a structure with a bound ligand is known. PROTAC: ubiquitination databases record sites on it; its protein half-life has been measured.
Gene: Protein-coding gene on chromosome 4 (163,494,442 to 163,520,733, forward strand). Ensembl gene ENSG00000198498.
Subcellular location: Nucleus
Subcellular location (Human Protein Atlas): Nucleoli; Nucleoplasm
Gene Ontology:
Molecular function: preribosome binding; protein binding; protein-macromolecule adaptor activity
Biological process: ribosomal large subunit biogenesis
Cellular component: nucleolus; nucleoplasm; nucleus
Genetic constraint (gnomAD): Loss-of-function variants: 23 observed, 20.33 expected, observed/expected ratio (o/e) 1.13, 90% interval 0.81 to 1.6. The upper end of that interval is the gene's LOEUF score, 1.6, which puts it in group 6 of 6, group 1 being the genes least tolerant of losing a copy. Missense variants: 204 observed, 203.31 expected, observed/expected ratio (o/e) 1, 90% interval 0.89 to 1.13. Synonymous variants: 65 observed, 71.43 expected, observed/expected ratio (o/e) 0.91, 90% interval 0.74 to 1.12.
Homologues: Orthologues: chimpanzee TMA16 (99% identical), macaque TMA16 (97% identical), dog TMA16 (88% identical), rabbit TMA16 (88% identical), pig TMA16 (81% identical), rat Tma16 (78% identical), mouse Tma16 (77% identical), guinea pig TMA16 (76% identical), zebrafish tma16 (58% identical), tropical clawed frog tma16 (57% identical), Drosophila melanogaster CG15027 (28% identical).
Diseases named in the same sentence as TMA16 in open-access papers:
TMA16 is named in the same sentence as 1 disease in open-access papers, as found by Europe PMC text mining. Sharing a sentence is not in itself a finding about the gene and the disease. The quoted sentences say what the papers report.
epilepsy (1 paper, 2024). A brain disorder characterized by episodes of abnormally increased neuronal discharge resulting in transient episodes of sensory or motor neurological dysfunction, or psychic dysfunction. "Based on the literature and database searches, there is association with seizures or epilepsy for five of the brain expressed genes (Marchf1, Tma16, Npy1r, Npy5r, Psd3)." (PMID 38862622, 2024).